SCARA3 (scavenger receptor class A member 3)
Diseases named in the same sentence as SCARA3 in open-access papers:
SCARA3 is named in the same sentence as 36 diseases in open-access papers, as found by Europe PMC text mining. Sharing a sentence is not in itself a finding about the gene and the disease. The quoted sentences say what the papers report.
myeloma (9 papers, 2015 to 2025). "Myeloma progression was associated with decreased SCARA3 mRNA expression in a retrospective analysis of human clinical myeloma samples." (PMID 39728572, 2024). "Other genes, SCARA3 was reported to be associated with poor prognosis in breast cancer, multiple myeloma, and prostate cancer." (PMID 28796819, 2017). "SCARA3 also plays a protective role against oxidative stress, which is a critical factor in the progression of various diseases, including multiple myeloma and other cancers." (PMID 40733561, 2025). "A clinical study demonstrated an inverse correlation between SCARA3 gene expression, myeloma progression, and SCARA3 expression." (PMID 35326105, 2022). "It is known that SCARA3 is downregulated in prostate cancer and myeloma, but upregulated in ovarian carcinoma." (PMID 35578316, 2022). "Additionally, increased SCARA3 mRNA expression was observed in a myeloma cell line, MM.IS, treated with the DNA methyltransferase inhibitor aza-dC, indicating epigenetic regulation." (PMID 39728572, 2024). "SCARA3 could be considered a tumor-repressor gene in multiple myeloma, since myeloma patients have increased markers of systemic oxidative stress." (PMID 39728572, 2024). "It has been reported that SCARA3 is downregulated in prostate cancer and myeloma." (PMID 35578316, 2022). "SCARA3 inhibits the lethal effect of dexamethasone and bortezomib on myeloma cells." (PMID 33490103, 2020). "The tumor necrosis factor-related apoptosis inducing ligand (TRAIL) receptor gene cluster as well as several other genes such as PTK2B and SCARA3 that might have a role in multiple myeloma progression and treatment resistance, lie in the p arm of chromosome 8." (PMID 26378933, 2015). "Besides, SCARA3 promotes drug resistance in multiple myeloma." (PMID 33198677, 2020). "An increased SCARA3 concentration reduced myeloma cell destruction operated by BTZ and dexamethasone and BTZ, while SCARA3 knockdown augmented the sensitivity of MM cells to these drugs." (PMID 35326105, 2022). "Scavenger receptor class A member 3 (SCARA3) is decreased in prostate cancer and myeloma." (PMID 35578316, 2022).
prostate carcinoma (8 papers, 2017 to 2025). A carcinoma that arises from epithelial cells of the prostate gland. "Promoter methylation of SCARA3 and its downregulation has also been demonstrated in prostate cancer." (PMID 39728572, 2024). "SCARA3 was statistically and significantly downregulated in lung, bladder, breast, colon, head and neck cancers, including previously reported prostate cancer." (PMID 35578316, 2022). "Finally, based on the report that the SCARA3 promoter region is hyper-methylated in prostate cancer, there is a possibility that hyper-methylation is also present in lung cancer." (PMID 35578316, 2022). "Furthermore, previous studies revealed that promoter methylation contributed to the down-regulation of SCARA3 in prostate cancer." (PMID 33318306, 2020). "It has been reported that miR-650 works as an oncomirna in hepatocellular carcinoma, colorectal cancer, prostate cancer, and gastric cancer, targeting ING4, NDRG2, and SCARA3 (also known as CSR1) TSG." (PMID 33086498, 2020). "When a genomic alteration of SCARA3 gene was analyzed in the TCGA-data of various cancers, the frequency of deep deletion was relatively high in lung, bladder, breast, colorectal, hand and neck, and prostate cancers where SCARA3 was downregulated in cancer tissues compared to that in normal tissues." (PMID 35578316, 2022).
glioblastoma (3 papers, 2020 to 2022). The most malignant astrocytic tumor (WHO grade IV). "used bioinformatics to identify four survival-associated differentially expressed genes (OSMR, HOXC10, SCARA3, and SLC39A10) in glioblastomas and found that glioblastoma patients with abnormal HOXC10 expression had poor survival outcomes." (PMID 34113572, 2021). "Chromosomal changes in the SCARA3 gene were found in 8 cancers except for thyroid and glioblastoma." (PMID 35578316, 2022). "SCARA3 was also involved in the signature for estimating the prognosis of glioblastoma." (PMID 33304907, 2020).
hepatocellular carcinoma (3 papers, 2020 to 2025). A malignant tumor that arises from hepatocytes. "In hepatocellular carcinoma SCARA3 was downregulated and shown to act as a tumor suppressor." (PMID 39728572, 2024).
lung carcinoma (2 papers, 2022 to 2025). "We found that SCARA3 was downregulated in lung cancer and that such downregulation was associated with a poor prognosis." (PMID 35578316, 2022). "Overexpression of SCARA3 caused a decrease in the Epithelial-Mesenchymal Transition (EMT) ability of lung cancer and an increase in sensitivity to cisplatin through AKT and JNK pathways." (PMID 35578316, 2022). "However, the low expression level of SCARA3 was significantly associated with a poor survival rate of lung cancer patients (p < 0.02224)." (PMID 35578316, 2022). "After overexpression of Flag-tagged-SCARA3 in H1299 and A549 lung cancer cells, cell growth rates were compared with those of the control cells." (PMID 35578316, 2022). "Compared with other lung cancer cells, H1299 cells exhibited cisplatin resistance and markedly reduced SCARA3 expression." (PMID 35578316, 2022). "As such, we found that SCARA3 overexpression increased the sensitivity of lung cancer to cisplatin treatment." (PMID 35578316, 2022). "Overexpression of SCARA3 inhibited lung cancer proliferation, reduced metastatic capacity, and decreased EMT marker proteins." (PMID 35578316, 2022). "Taken together, these results suggest that SCARA3 is closely related to the proliferation of lung cancer cells and that overexpressing SCARA3 can inhibit lung cancer cell proliferation." (PMID 35578316, 2022). "Taken together, these results suggest that SCARA3 can induce increased sensitivity of lung cancer to cisplatin via the AKT/JNK pathway." (PMID 35578316, 2022). "Migration and invasion of SCARA3 overexpressed lung cancer cells were determined using a Transwell chamber system." (PMID 35578316, 2022). "The level of SCARA3 expression in lung cancer cells was comparatively lower than that in normal cells." (PMID 35578316, 2022). "We aimed to prove the role of SCARA3 in the treatment of Lung cancer, and shown that the expression level of SCARA3 is important in cancer treatment using cisplatin." (PMID 35578316, 2022). "Using TCGA-data analysis, CCLE-RNA sequencing and GDSC data analysis, tissue microarray, cell systems, and xenograft model, we conclude that SCARA3 plays a major functional and clinical role in lung cancer." (PMID 35578316, 2022). "As lung cancer tumor grade increased, there was a gradual and significant decrease in SCARA3 expression level." (PMID 35578316, 2022). "The expression level of SCARA3 in the TCGA-database, lung cancer tissue microarray and lung cancer cells and the prognosis of lung cancer patients were measured." (PMID 35578316, 2022). "First, we focused on SCARA3 being downregulated in lung cancer and located in the chromosomal region 8p21." (PMID 35578316, 2022). "The chromosomal 8p21 region, where tumor suppressors such as TRAIL-receptor and MTSG1 as well as the SCARA3 gene are located, is frequently deleted in lung cancer." (PMID 35578316, 2022). "Consistent with the TCGA-lung data and immunohistochemistry results, significantly lower levels of SCARA3 protein and mRNA were detected in lung cancer cell lines than in normal primary human diploid lung fibroblasts (WI38, MRC5, IMR90)." (PMID 35578316, 2022). "In the present study, we confirmed that SCARA3 is a negative regulator of proliferation in lung cancer." (PMID 35578316, 2022). "The expression of SCARA3 was abnormally reduced in TCGA-database, lung tissue microarray, and various lung cancer cells." (PMID 35578316, 2022). "Overexpression of SCARA3 potently inhibited tumors in lung cancer and induced apoptosis by increasing sensitivity of lung cancer to cisplatin." (PMID 35578316, 2022). "Thus, the objective of this study was to determine the expression and role of SCARA3 in lung cancer." (PMID 35578316, 2022). "Taken together, our results indicate that SCARA3 is a major biomarker of lung cancer and that the induction of SCARA3 overexpression in cisplatin-resistant lung cancer patients might be an effective treatment strategy." (PMID 35578316, 2022).
lung carcinoma (continued). "We tested whether the role of SCARA3 in inhibiting the proliferation of lung cancer was maintained not only in cell culture experiments conducted under artificial conditions, but also in an in vivo environment." (PMID 35578316, 2022). "Interestingly, SCARA3 overexpression reduced the migration and invasion ability of lung cancer cells and induced a decrease in EMT marker protein." (PMID 35578316, 2022). "From this point of view, our results can infer that SCARA3 might be a tumor suppressor candidate in lung cancer." (PMID 35578316, 2022). "Therefore, there is a need to analyze SCARA3 promoter methylation and study sumoylation of SCARA3 protein in lung cancer treatment using SCARA3 expression regulation." (PMID 35578316, 2022). "This study confirmed that SCARA3 was downregulated in lung cancer." (PMID 35578316, 2022). "Considering that SCARA3 expression was decreased in lung cancer tissues and cells, SCARA3 expression might have an effect on lung cancer proliferation." (PMID 35578316, 2022). "In addition, SCARA3 overexpression increased the sensitivity of lung cancer to cisplatin and induced death of lung cancer cells." (PMID 35578316, 2022). "We predicted that overexpressing SCARA3 could reduce the ability of Epithelial-Mesenchymal Transition (EMT) in lung cancer." (PMID 35578316, 2022). "In this study, we tried to evaluate the functional study of SCARA3 in lung cancer." (PMID 35578316, 2022). "SCARA3 was also downregulated in lung cancer tissues compared to that in normal tissues." (PMID 35578316, 2022). "SCARA3 overexpression inhibited lung cancer cell proliferation." (PMID 35578316, 2022). "This study confirmed an abnormal decrease in SCARA3 in lung cancer." (PMID 35578316, 2022). "In addition, overexpression of SCARA3 reduced migration and invasion ability of lung cancer cells and induced decreases of EMT markers such as β-catenin, vimentin, and MMP9." (PMID 35578316, 2022). "However, overexpression of SCARA3 reduced the proliferation of lung cancer." (PMID 35578316, 2022). "We predicted that SCARA3 could also be down-regulated in other cancers such as lung cancer." (PMID 35578316, 2022). "However, the expression level of SCARA3 in lung cancer remains unclear." (PMID 35578316, 2022). "In addition, to investigate the clinical significance of SCARA3 in lung cancer specimens, tissue microarray (TMA) data were analyzed for lung cancer tissues composed of different grades of carcinoma." (PMID 35578316, 2022). "We found a negative correlation of SCARA3 expression with cisplatin IC50 in lung cancer cells, which was statistically significant (r = − 0.2205, p < 0.0138)." (PMID 35578316, 2022). "The correlation between SCARA3 expression level and cisplatin IC50 in 11 tested lung cancer cell lines was not significant (r = − 0.5889, p = 0.0623) by Pearson’s correlation analysis." (PMID 35578316, 2022).
osteoporosis (2 papers, 2021 to 2024). A condition of reduced bone mass, with decreased cortical thickness and a decrease in the number and size of the trabeculae of cancellous bone (but normal chemical composition), resulting in increased fracture incidence. "This study suggested that Scara3 regulated the switch between adipocyte and osteoblast differentiation, which represented a potential therapeutic target for bone loss and osteoporosis." (PMID 34254370, 2021). "Balla et.al18, 19 demonstrated that SCARA3 transcription was significantly downregulated in osteoporosis bone tissue, but they did not further explored the functional roles of SCARA3 in bone formation." (PMID 34254370, 2021).
asthma (1 paper, 2018). "Furthermore, the expression levels of the known IRE1α–RIDD target genes Hqsnat, Blos1, Scara3, Pdqfrb, Pmp2 and Col6 were decreased in OVA/LPS-induced asthma and recovered with IC87114 administration." (PMID 29504610, 2018).
atherosclerosis (1 paper, 2020). A disease characterized by the build-up of fatty material and calcium deposition in the arterial wall resulting in partial or complete occlusion of the arterial lumen. "Moreover, hypermethylation of SCARA3 was observed in patients with type 2 diabetes and atherosclerosis." (PMID 33318306, 2020).
glioma (1 paper, 2020). A benign or malignant brain and spinal cord tumor that arises from glial cells (astrocytes, oligodendrocytes, ependymal cells). "This study identified the MAGs of IDH wild-type glioma and the prognostic model was constructed by genes including GNS, LBH and SCARA3." (PMID 33198677, 2020).
Glucose intolerance (1 paper, 2020). Glucose intolerance (GI) can be defined as dysglycemia that comprises both prediabetes and diabetes. "Intriguingly, the results implied that SCARA3 is associated with several metabolic disorders, such as weight loss, weight gain, glucose intolerance and insulin resistance." (PMID 33318306, 2020). "In addition, the data from the CTD database showed that SCARA3 is associated with several metabolic disorders, such as weight loss, weight gain, glucose intolerance and insulin resistance." (PMID 33318306, 2020).
head and neck cancer (1 paper, 2022). A primary or metastatic malignant neoplasm affecting the head and neck. "In breast and head and neck cancers, SCARA3 was downregulated in cancer tissues compared to that in normal tissues." (PMID 35578316, 2022).
Obesity (1 paper, 2020). Accumulation of substantial excess body fat. "Collectively, our study suggested that SCARA3 is potentially associated with age-related metabolic dysfunction, which provided new insights into the pathogenesis and treatment of obesity as well as other obesity-associated metabolic complications." (PMID 33318306, 2020). "Thus, the results of the present study suggested that SCARA3 is a potential new target for diagnosis and treatment of obesity, as well as other obesity-associated metabolic complications." (PMID 33318306, 2020). "To investigate the role of adipose tissue-derived mesenchymal stem cells (Ad-MSCs) in obesity, we analyzed the expression of Scara3 in Ad-MSCs from GSE115068." (PMID 33318306, 2020). "Collectively, we hypothesized that SCARA3 contributes to obesity and obesity-related metabolic complications in an age-dependent manner." (PMID 33318306, 2020). "However, the role of scavenger receptor class A member 3 (SCARA3) in obesity-related disorders has been rarely reported." (PMID 33318306, 2020). "Together, the present study combining bioinformatic analysis with the several biochemical functional analyses in vitro and in vivo, provided strong supports for the hypothesis that SCARA3 is a potential target for the treatment of obesity and other metabolic disorders." (PMID 33318306, 2020).
ovarian carcinoma (1 paper, 2022). A malignant neoplasm originating from the surface ovarian epithelium. "The upregulation of SCARA3 during disease progression from diagnosis to recurrence suggests that it plays a role in ovarian cancer biology." (PMID 36117173, 2022).
type 2 diabetes (1 paper, 2020). "A previous study reported increased methylation of SCARA3 in patients with type 2 diabetes mellitus." (PMID 33318306, 2020). "Here, we also found that SCARA3 methylation had some correlations with metabolic diseases, such as atherosclerotic lesions and type 2 diabetes via a search on the DiseaseMeth version 2.0 database." (PMID 33318306, 2020). "A previous study indicated that elevated methylation of SCARA3 probably disturbed the oxidative stress protection in type 2 diabetes mellitus (T2DM)." (PMID 33318306, 2020).
ZIKV infection (1 paper, 2025). "To determine activation of the IRE1 endonuclease activity through the RIDD branch during ZIKV infection in human microglia, we measured expression of canonical RIDD targets Bloc1s1, Scara3, and Per1." (PMID 41157563, 2025).
tumor (8 papers, 2020 to 2025). "Correspondingly, tumor tissues xenografted with SCARA3-deficient A549 cells showed increased ki67 protein." (PMID 35578316, 2022). "In contrast, SCARA3 deficiency increased cell growth rate and tumor sphere formation in A549." (PMID 35578316, 2022). "SCARA3 deficiency significantly increased xenograft tumor growth compared to the control." (PMID 35578316, 2022). "Consistently, when tumor sphere formation analysis was performed, the tumor sphere diameter (mm3) was decreased by (1.76–2.61)-fold due to SCARA3 overexpression." (PMID 35578316, 2022). "When xenograft tumor tissues were isolated and analyzed by immunohistochemistry, overexpression of SCARA3 protein decreased the expression level of proliferation-specific marker ki67 protein." (PMID 35578316, 2022). "When flag-tagged SCARA3 was overexpressed, xenograft tumor growth was significantly reduced compared to that of the control group." (PMID 35578316, 2022). "IHC analysis of xenografted tumour tissues revealed that MPZ, SCARA3, MPP2 and PBXIP1 expression levels were low in the SW620/sh-MPZ, SW620/sh-SCARA3, SW620/sh-MPP2 and SW620/sh-PBXIP1 groups." (PMID 36117173, 2022).
cancer (7 papers, 2016 to 2025). A tumor composed of atypical neoplastic, often pleomorphic cells that invade other tissues. "Inhibition of cancer cell proliferation caused by SCARA3 overexpression using a xenograft model was maintained in an in vivo environment." (PMID 35578316, 2022). "Our results are very important in that our results show that SCARA3 can both reduce the size of cancer and inhibit the metastasis ability." (PMID 35578316, 2022). "The ability of SCARA3 to inhibit cancer cell proliferation was maintained even in vivo using a mouse xenograft model." (PMID 35578316, 2022). "The second result we noted is the role of SCARA3 in cancer cell proliferation and metastasis ability." (PMID 35578316, 2022). "To prove this, we analyzed SCARA3 mRNA levels in normal and cancer tissues of 10 cancers using the TCGA-database." (PMID 35578316, 2022). "Therefore, we analyzed the alteration frequency of SCARA3 in the TCGA-database of various cancers." (PMID 35578316, 2022). "However, functions of SCARA3 in various cancers remain unclear." (PMID 35578316, 2022). "For unreported model genes (MPZ, SCARA3, MPP2 and PBXIP1), recent studies have demonstrated that those genes are involved in the development of cancers." (PMID 36117173, 2022). "However, studies on the functional role of SCARA3 in cancer are lacking." (PMID 35578316, 2022).
infection (1 paper, 2023). The state of being infected such as from the introduction of a foreign agent such as serum, vaccine, antigenic substance or organism. "However, BLOC1S1, SCARA3, COL6A1, and HGSNAT were unaffected by HCoV-OC43, suggesting that IRE1α activity is limited to XBP1 splicing during infection." (PMID 37306512, 2023).
metabolic disorders (1 paper, 2020). "Taken together, these results revealed the potentially important roles of SCARA3 in metabolic disorders." (PMID 33318306, 2020). "Data from the CTD database indicated that SCARA3 is a potential target for metabolic diseases." (PMID 33318306, 2020).
SCARA3 also shares sentences with these, for which no sentence is quoted: multiple myeloma (5 papers); breast carcinoma (3); Alzheimer disease (1); and Mouth Disease (1); bacterial disease (1); colorectal cancer (1); colorectal tumour (1); gastric cancer (1); gastroesophageal reflux disease (1); gastrointestinal disorders (1); Hypercalciuria (1); Infertility (1); Insulin resistance (1); thyroid (1); type 2 diabetes mellitus (1); ulcerative colitis (1); Wilson disease (1).